IDH2 (isocitrate dehydrogenase (NADP(+)) 2)
Diseases named in the same sentence as IDH2 in open-access papers (continued):
Sharing a sentence is not in itself a finding about the gene and the disease.
glioma (continued). "To examine the potential impact of mutant IDH2 specific inhibitor on our IDH2 mutant glioma cells, we performed cell viability assay and western blots." (PMID 38012788, 2023). "Other variants, such as IDH2, BRAF, and PIK3A, had low-frequency and were mainly present in patients with other gliomas, while low-frequency EGFR variants were more common in GBM patients." (PMID 36959606, 2023). "Substitution point mutations in IDH1 (R132H) and IDH2 (R172K; R140Q) are common events in low-grade (II/III) glioma (> 75%) and acute myeloid leukemias (AML) (20%), but rare in other cancers." (PMID 38066546, 2023). "Mutations in the NADP+-dependent isocitrate dehydrogenase genes IDH1 and IDH2 are common in acute myeloid leukemia and gliomas." (PMID 36984785, 2023). "IDH mutations in gliomas mostly relate to isotype 1 (IDH-1) and less frequently to isotype 2 (IDH-2)." (PMID 37626776, 2023). "Cartilage tumours and cholangiocarcinoma mainly have IDH1 p.R132C variants (~60%), glioma predominantly harbours IDH1 p.R132H mutations (~90%), and AML often has IDH2 p.R140Q mutations (~40%)." (PMID 37509266, 2023). "A total of 115 glioma patients were included, of which 82 (71.3%) patients expressed IDH1 gene mutation and five (4.35%) patients expressed IDH2 gene mutation." (PMID 37250582, 2023). "IDH (IDH1 and IDH2) genotype and 1p/19q status are important molecular biomarkers in the clinical diagnosis and prognosis evaluation of gliomas." (PMID 37734869, 2023). "Glioma samples tested by the brain subpanel had BRAF variants at 8% and IDH1/IDH2 variants at 12.5%." (PMID 37483495, 2023). "Frequent mutations of IDH1 and IDH2 have been found in various tumors, such as acute myeloid leukemia (AML), glioma, and chondrosarcoma." (PMID 37563735, 2023). "IDH2, which is an analog of IDH1, is predominantly localized in mitochondria but mutated in gliomas at much lower frequencies." (PMID 37108511, 2023). "As adult-type gliomas commonly harbor IDH1 (and less commonly, IDH2) mutations, testing the efficacy of IDH inhibitors in these tumors has become a research focus in recent years." (PMID 37781183, 2023). "IDH1 (and IDH2) were the most predictive for long‐term survival, once again supporting the idea of considering IDHmt grade IV glioma as a distinct category in the 2021 WHO classification of central nervous system (CNS) tumors." (PMID 36776000, 2023). "For example, approximately 20–30% of infiltrative gliomas carry mutations in isocitrate dehydrogenase 1 (IDH1) or, far less commonly, IDH2 (together referred to as “IDHmut”)." (PMID 35134075, 2022). "There is a phase II clinical trial that is specifically designed to look at the effectiveness of nivolumab in patients with IDH1 or IDH2 hypermutated gliomas (hypermutator phenotype) currently recruiting (NCT03718767)." (PMID 35203636, 2022). "Since its initial discovery in gliomas, IDH1 and IDH2 mutations have been described in a variety of other cancers including acute myeloid leukaemia, thyroid carcinomas, cartilaginous tumours such as enchondroma and chondrosarcoma, and cholangiocarcinomas." (PMID 36286062, 2022). "Most sporadic adult diffuse grade II and III gliomas harbor mutations of the IDH1 and/or IDH2 genes, which is considered the first event driving oncogenesis of these tumors." (PMID 35884525, 2022).
glioma (continued). "In 2016, the World Health Organization (WHO) classification of gliomas used molecular parameters including isocitrate dehydrogenase 1 and 2 (IDH1 and IDH2) mutations and 1p/19q codeletion status in addition to histopathological criteria." (PMID 35615996, 2022). "In particular, IDH1 and IDH2 are present in over 80% of low-grade gliomas and a subset of adult glioblastomas." (PMID 35382567, 2022). "The oncometabolite 2-hydroxyglutarate, produced by mutant IDH1 and IDH2-encoding enzymes, influences TAM composition in high-grade gliomas." (PMID 35513201, 2022). "There are three isoforms of the IDH gene, of which the most important in gliomas are cytosolic IDH1 and mitochondrial IDH2 mutations; most IDH-mutated gliomas harbor IDH1 mutations in the form of IDH (R132H)." (PMID 35693015, 2022). "Aggressive gliomas, which include GBM, harbor wild-type IDH1 and IDH2 genes (IDHwt), whereas gliomas with better prognosis carry mutated IDH1 and IDH2 genes (IDHmut)." (PMID 35563134, 2022). "In this study, we evaluated the use of a DNA methylation array to simultaneously identify the two most important biomarkers of glioma: IDH1/IDH2 status and 1p19q co-deletion." (PMID 36360312, 2022). "IDH1 R132 or IDH2 R172 mutant gliomas usually arise in a younger patient population, and patients with low grade gliomas (LGG) typically have a long overall survival time (5–10 years)." (PMID 35216362, 2022). "Furthermore, gliomas with mutated isocitrate dehydrogenase (IDH1 and IDH2) showed elevated levels of oncometabolite D-2-hydroxyglutarate derived from glutamine via glutamate and α-KG conversion, demonstrating the importance of glutamine metabolism in the malignant progression of gliomas." (PMID 35513201, 2022). "These mutations, however, are not decisive for the development of epilepsy, as IDH1 and IDH2 mutations do increase the risk of developing seizures in gliomas, while LEATs typically lack IDH1 or IDH2 mutations and 1p/19q co-deletions." (PMID 36289737, 2022). "The most studied example linking genetic alterations to gliomas metabolic changes is the acquired mutation in IDH1 and/or IDH2 genes." (PMID 35912242, 2022). "The investigated ddPCR-based assays enable the detection of diagnostically relevant glioma-associated mutations in the IDH1, IDH2, H3-3A, BRAF, and PRKCA genes, as well as in the TERT promoter." (PMID 35361262, 2022). "A sequence of human tumors for IDH1 or IDH2 mutations, or monoclonal antibodies against the most common IDH1 mutation (R132H), allows for immunohistochemical analysis of low-grade gliomas and GBMs." (PMID 35806212, 2022). "These same IDH1 and IDH2 variants have been reported in many cancers such as acute myeloid leukemia (AML) and glioma where co-occurrence with variants in other genes is a common mechanism." (PMID 36480544, 2022). "This study examines the effectiveness of olaparib in treating cholangiocarcinoma, glioma, and solid tumors which have mutations in the IDH1 or IDH2 gene; unable to treat or control with current treatments; have migrated to other parts of the body." (PMID 35873570, 2022). "Initial studies using methylation data from the Illumina GoldenGate array had characterized CIMP in glioma tumors, which was associated with both glioma histological subtype and IDH1/IDH2 mutations." (PMID 36360312, 2022). "IDH has three isomerase forms (IDH1/2/3), of which IDH1 and IDH2 are important indicators of glioma molecular classification, which are of great significance for the diagnosis, individualized treatment, and prognosis of gliomas." (PMID 35807084, 2022).
glioma (continued). "The LGG cases under study were classified into four groups based on genetic characteristics agreeing with WHO 2021 stratification of gliomas: The IDH-wt group collects unmutated (wild type) IDH1 and/or IDH2 (IDH) gliomas." (PMID 35681780, 2022). "We performed methylome profiling of glioma tissues (GBM WHO IV) and the primary GBM cells derived from the tissues were characterized for the mutational status of IDH1/IDH2 and methylation of MGMT as described in Materials and Methods." (PMID 35393392, 2022). "With the development of sequencing technology, IDH1 or IDH2 mutations have been found in various malignant tumors, such as AML, glioma, chondrosarcoma." (PMID 33981605, 2021). "Mutations affecting IDH2 and additional IDH1 variants have also been reported in gliomas, but at a lower frequency, with the majority conferring similar changes in IDH activity." (PMID 34277624, 2021). "IDH mutations identified in gliomas tend to occur at the active site of the enzyme at arginine 132 and 172 in IDH1 and IDH2, respectively." (PMID 34675774, 2021). "Specifically, IDH1 and IDH2 are wild‐type (IDHwt) in the most aggressive glioma types, which include about 95% of GBM, whereas they are mutated (IDHmut) in gliomas with better prognosis." (PMID 33720519, 2021). "IDH1 and IDH2 genes encode isocitrate dehydrogenase 1 (IDH1) and isocitrate dehydrogenase 2 (IDH2) in gliomas." (PMID 34961815, 2021). "Among these subtypes, point mutations in IDH1 and IDH2 have been reported in gliomas of grade II and III developed from low-grade glioma." (PMID 33562094, 2021). "Following the discoveries in glioma and AML, mutations in IDH2 gene were found in multiple types of human tumors, including thyroid carcinomas, cartilaginous tumors, and intrahepatic cholangiocarcinoma." (PMID 34641967, 2021). "IDH mutations in gliomas occur more frequently at residue p.R132 of IDH1 and residue p.R172 of IDH2." (PMID 34165590, 2021). "Somatic mutations, such as R132H in IDH1 and R140Q or R172H in IDH2 have been found in various types of human cancers, including AML, glioma, chondrosarcoma and so on." (PMID 34425876, 2021). "Overall, approximately 80% of lower-grade gliomas and secondary glioblastomas harbor an IDH1 or IDH2 mutation, thus supporting the inclusion of this class of mutations in mouse models of these glioma subtypes." (PMID 33806933, 2021). "Missense mutations in codon 132 of IDH1 or codon 172 of IDH2 are the defining molecular feature of IDH-mutant astrocytomas and are associated with the glioma CpG island methylator phenotype (G-CIMP)." (PMID 33293629, 2021). "This phenomenon suggests that IDH2 plays a carcinogenic role in gastric cancer cells, which is similar to the effect of IDH2 on low-grade gliomas." (PMID 33981605, 2021). "Small populations of IDH2-mutated gliomas were identified as well, with 6% (18/281) of IDH1/2-mutated gliomas harboring IDH2 R172 mutations." (PMID 33778493, 2021). "2HG is an oncometabolite, produced in glial tumor cells bearing an isocitrate dehydrogenase (IDH) gene mutation, either IDH1 or IDH2." (PMID 35340697, 2021). "The discovery of mutations in isocitrate dehydrogenase 1 (IDH1) or isocitrate dehydrogenase 2 (IDH2) genes in glial brain tumors critically shaped the understanding of the clinical importance of molecular differences in gliomas." (PMID 33216206, 2021). "Therefore, IDH1 and IDH2 mutations may be involved in the tumorigenesis of gliomas." (PMID 34961815, 2021). "Amongst the molecular genetic alterations used to redefine glioma entities, the most common are mutations in the isocitrate dehydrogenase 1 and 2 (IDH1, IDH2) genes and the 1 p/19q co-deletion status." (PMID 33916593, 2021).
glioma (continued). "The brain-penetrant dual inhibitor of IDH1 and IDH2, vorasidenib, is currently under development in recurrent/refractory IDH-mutated glioma." (PMID 34083508, 2021). "Noteworthy, all our IDH2-mutant gliomas resulted oligodendroglial, reinforcing the reported association between IDH2 mutations and 1p/19q codeletion in diffuse gliomas." (PMID 34165590, 2021). "Mutations in gliomas often occur in IDH1 and IDH2, both of which caused the conversion of α-ketoglutarate (α-KG) to 2-hydroxyglutarate (2-HG) in a NADPH-dependent manner." (PMID 34211978, 2021). "The mutations observed in IDH enzymes in gliomas are mainly in cytosolic IDH1 and mitochondrial IDH2, most frequently at codons R132 and R172, respectively." (PMID 34356864, 2021). "IDH2 mutations are mutually exclusive with IDH1 mutations, and thus far, have been found rarely (3.3%) in WHO grade II or III gliomas and much rarely (less than 1%) in GBMs." (PMID 33981605, 2021). "High frequent mutations in IDH2 have been found in AML, glioma, chondrosarcoma, angioimmunoblastic T cell lymphoma (AITL) and solid papillary carcinoma with reverse polarity (SPCRP), and IDH2 mutations were also reported in other malignant tumors." (PMID 33981605, 2021). "We found that the 2HG detection by MRS was useful in the selection of glioma cases with rare IDH1 and IDH2 mutations." (PMID 34829476, 2021). "Gliomas patients harboring IDH mutations, including IDH1 and IDH2 mutation, have a better prognosis than the wild type." (PMID 34961815, 2021). "Sixty-six of the 69 gliomas were IDH-mutant: 61 had IDH1 R132H mutations detected by immunohistochemistry (IHC); 5 had IDH2 mutations detected at sequencing analysis, including 2 ODs and 1 AOD with a R172K mutation and 2 AODs with a R172M mutation." (PMID 34165590, 2021). "IDH1/2 mutations are ideal tumor-specific antigens because they occur at specific codons in IDH1 and IDH2 and are commonly found in glioma cells." (PMID 34603319, 2021). "Patients with lower-grade gliomas (grades II-III) and glioblastoma show significantly longer OS in the presence of IDH1 or IDH2 mutations." (PMID 34178638, 2021). "Point mutations at codons Arg132 of the IDH1 gene and Arg172 of the IDH2 genes were identified in 25 out of 60 (41.7%) gliomas." (PMID 32599896, 2020). "Approximately 80% of low-grade gliomas harbor recurrent mutations in the isocitrate dehydrogenase genes 1 and 2 (commonly referred to as IDH1 and IDH2, respectively)." (PMID 33066121, 2020). "Point mutations of two arginine residues, R140Q and R172K in the active site of IDH2, can drive the development of leukemia and glioma in vivo." (PMID 32245484, 2020). "Central chondrosarcoma and cholangiocarcinoma predominantly harbour R132C mutations in IDH1 (50%), glioma has mainly R132H mutations in IDH1 (90%) and AML has most often R140Q mutations in IDH2 (30–50%)." (PMID 31728625, 2020). "Nearly 80% of World Health Organization Grades II and III gliomas show the presence of mutation in the IDH1 and IDH2 genes that regulate the omonimous enzymes." (PMID 33178960, 2020). "Based on two hallmarks of glioma, mutation of IDH1 and IDH2 genes, and codeletion of chromosome arms 1p/19q, glioma is primarily distinguished into five principle molecular subtypes." (PMID 33747896, 2020). "It was recognized that gliomas bearing IDH2 mutants accumulated more 2HG than those with IDH1 mutants." (PMID 31847543, 2020). "To date, in human gliomas, only heterozygotic mutations in IDH-1 and IDH-2 have been reported, with a significant preponderance of IDH-1." (PMID 33212941, 2020). "The inhibitor of mutant IDH1 ivosidenib and mutant IDH2 enasidenib exhibited positive responses in patients with relapsed or refractory gliomas, intrahepatic cholangiocarcinomas, and chondrosarcomas in phase I/II clinical trials." (PMID 31847543, 2020). "Previous studies have confirmed the role of IDH1 and IDH2 driver mutations in tumorigenesis of AML and gliomas." (PMID 32333643, 2020).
glioma (continued). "IDH 1 mutation is present in over 80% of secondary GBMs, while IDH2 gene have been reported in around 3% of gliomas." (PMID 32212804, 2020). "Briefly, somatic mutations affecting the R132 residue of the isocitrate dehydrogenase 1 (IDH1) or R172 residue of the isocitrate dehydrogenase 2 gene (IDH2) are often detected in WHO grade II or III gliomas and oligodendrogliomas." (PMID 32013066, 2020). "Mutations in the IDH1 or IDH2 genes have been detected in a large number of adult diffuse grade II and grade III gliomas; such high frequency has suggested a possible role for those variants as the earliest oncogenic event in these malignancies." (PMID 33282797, 2020). "In 2016 WHO classification, mutations in the epigenetic modulator genes isocitrate dehydrogenase 1 or 2 (IDH1 or IDH2) and codeletion of chromosomal arms 1p/19q (1p/19q codel) have become key biomarkers for glioma classification." (PMID 32373523, 2020). "The frequency of IDH1 and IDH2 mutations are different in various tumor types: Thus, IDH1 and IDH2 are almost equally frequent in AML, while IDH1 mutations are predominant in gliomas, chondrosarcomas, and cholangiocarcinomas." (PMID 32859092, 2020). "IDH1 mutations occur at much higher incidences than IDH2 mutations in lower grade glioma (WHO grade II and III gliomas, LGG)." (PMID 32280672, 2020). "This is the case of mutations in IDH1 or IDH2 in lower-grade gliomas, and histone 3 (H3F3A and HIST1H3B) mutations in pediatric high-grade gliomas that are also associated with specific patterns of DNA methylation." (PMID 31968687, 2020). "IDH1 and IDH2 exhibit high sequence similarity and are often present in various malignancies, including glioma, leukemia, and cartilaginous tumors." (PMID 33014795, 2020). "For gliomas, mutation at Arg132 of IDH1, and at the analogous codon Arg172 of IDH2, represents early initiating events that drive the evolution of low-grade glioma, including grade II to III astrocytoma and oligodendroglioma." (PMID 32280672, 2020). "IDH1 and IDH2 mutations also frequently occur in for instance acute myeloid leukaemia (AML), glioma and cholangiocarcinoma." (PMID 31728625, 2020). "Mutation of the gene encoding isocitrate dehydrogenase (NADP(+)) 1, (IDH1) at arginine 132 or IDH2 at arginine 172 is associated with secondary GBM, GBM that has arisen from lower grade glioma." (PMID 30894629, 2019). "Gliomas are now characterized based on the presence of mutations in the isocitrate dehydrogenase family of genes (IDH1 and IDH2)." (PMID 30823903, 2019). "The excellent spectral quality obtained at 7T enabled us to detect elevated 2-HG concentrations in glioma patients harboring common (i.e., IDH1 R132H) and rare IDH mutations (i.e., IDH2 R172K and R172W)." (PMID 30791611, 2019). "High-throughput DNA sequencing of human gliomas identified mutually exclusive somatic mutations in either IDH1 or IDH2 in approximately 70% of secondary glioblastomas and grade II–III gliomas." (PMID 31105869, 2019). "AG-881(Vorasidenib), a pan-inhibitor of both mutant IDH1 and mutant IDH2, exhibits effective brain penetration accompanied by suppression of 2-HG production in an orthotopic glioma model (IDH1 R132H)." (PMID 31652645, 2019). "Further studies have found that IDH1, or IDH2 mutation, happens in ~80% of WHO grade II–III gliomas and secondary GBM." (PMID 31450721, 2019). "A two-sample t-test was used for metabolite comparisons between IDH1 (n = 15) and IDH2 (n = 5) mutant gliomas." (PMID 30791611, 2019). "Over the last decade the understanding of glioma tumorigenesis was substantially increased due to the discovery of mutations involving the genes encoding isocitrate dehydrogenase 1 and 2 (IDH1/IDH2) enzymes." (PMID 31242696, 2019). "Homologous mutations in the metabolic enzymes isocitrate dehydrogenase 1 and 2 (IDH1 and IDH2) are found in acute myelogenous leukemia, colon cancer and glioma." (PMID 29692895, 2018).